ASCC2 (activating signal cointegrator 1 complex subunit 2)
Description:
Ubiquitin-binding protein involved in DNA repair and rescue of stalled ribosomes. Plays a role in DNA damage repair as component of the ASCC complex. Recruits ASCC3 and ALKBH3 to sites of DNA damage by binding to polyubiquitinated proteins that have 'Lys-63'-linked polyubiquitin chains. Part of the ASC-1 complex that enhances NF-kappa-B, SRF and AP1 transactivation. Involved in activation of the ribosome quality control (RQC) pathway, a pathway that degrades nascent peptide chains during problematic translation. Specifically recognizes and binds RPS20/uS10 ubiquitinated by ZNF598, promoting recruitment of the RQT (ribosome quality control trigger) complex on stalled ribosomes, followed by disassembly of stalled ribosomes.
Synonyms: ASC1P100; FLJ21588; DKFZp586O0223; p100
Tractability: PROTAC: ubiquitination databases record sites on it; its protein half-life has been measured.
Gene: Protein-coding gene on chromosome 22 (29,788,608 to 29,838,304, reverse strand). Ensembl gene ENSG00000100325.
Subcellular location: Nucleus; Nucleus speckle
Subcellular location (Human Protein Atlas): Cytosol; Focal adhesion sites; Nucleoplasm
Pathways (Reactome):
DNA Repair: ALKBH3 mediated reversal of alkylation damage
Metabolism of proteins: ZNF598 and the Ribosome-associated Quality Trigger (RQT) complex dissociate a ribosome stalled on a no-go mRNA
Gene Ontology:
Molecular function: K63-linked polyubiquitin modification-dependent protein binding; protein binding; ubiquitin binding
Biological process: regulation of DNA-templated transcription; rescue of stalled ribosome; ribosome disassembly; ribosome-associated ubiquitin-dependent protein catabolic process; DNA alkylation repair; DNA replication
Cellular component: cytosolic ribosome; DNA repair complex; nuclear speck; nucleus; RQC-trigger complex; cytosol; nucleoplasm
Genetic constraint (gnomAD): Loss-of-function variants: 41 observed, 89.69 expected, observed/expected ratio (o/e) 0.46, 90% interval 0.35 to 0.59. The upper end of that interval is the gene's LOEUF score, 0.59, which puts it in group 2 of 6, group 1 being the genes least tolerant of losing a copy. Missense variants: 847 observed, 984.07 expected, observed/expected ratio (o/e) 0.86, 90% interval 0.81 to 0.91. Synonymous variants: 361 observed, 383.55 expected, observed/expected ratio (o/e) 0.94, 90% interval 0.86 to 1.03.
Homologues: Orthologues: chimpanzee ASCC2 (99% identical), macaque ASCC2 (98% identical), rabbit ASCC2 (91% identical), pig ASCC2 (90% identical), guinea pig ASCC2 (89% identical), rat Ascc2 (87% identical), mouse Ascc2 (87% identical), dog ASCC2 (84% identical), tropical clawed frog ascc2 (60% identical), zebrafish ascc2 (55% identical), Drosophila melanogaster CG2701 (27% identical).
Diseases named in the same sentence as ASCC2 in open-access papers:
ASCC2 is named in the same sentence as 11 diseases in open-access papers, as found by Europe PMC text mining. Sharing a sentence is not in itself a finding about the gene and the disease. The quoted sentences say what the papers report.
congenital bone fractures (1 paper, 2021). "This complex includes ASCC1 (associated with spinal muscular atrophy with congenital bone fractures 2), TRIP4 (associated with spinal muscular atrophy with congenital bone fractures 1), and ASCC2 (not yet associated with human disease)." (PMID 35047834, 2021).
rectal adenocarcinoma (1 paper, 2025). "Next, we analyzed the expression levels of ASCC3, ASCC1, ASCC2, and TRIP4 in TCGA rectal adenocarcinoma samples." (PMID 40881169, 2025).
tumor (3 papers, 2017 to 2026). "The results slightly differed from those of TCGA, with ASCC3 and ASCC1 being more highly expressed in tumor tissue, while ASCC2 and TRIP4 were significantly expressed in normal tissue." (PMID 40881169, 2025). "Functionally, co-targeting DLEU1 and ASCC2 synergized with G6PD inhibition, significantly impairing GC cells viability and tumor growth." (PMID 41484982, 2026). "Functionally, dual silencing of DLEU1 and ASCC2, in combination with G6PD inhibition, synergistically suppressed the viability of GC cells and tumor growth in vivo, highlighting the therapeutic potential of targeting the DLEU1/ASCC2/G6PD axis." (PMID 41484982, 2026). "Targeting the DLEU1/ASCC2/G6PD axis significantly suppresses GC cells proliferation and tumor growth, proposing a therapeutic strategy targeting this pathway." (PMID 41484982, 2026). "Furthermore, the progressive suppression of ASCC2, ALKBH3, E2F1, and G6PD led to a marked decrease in their immunohistochemical staining scores, indicating reduced protein expression and altered cellular localization within the tumor microenvironment." (PMID 41484982, 2026).
cancer (2 papers, 2020 to 2021). A tumor composed of atypical neoplastic, often pleomorphic cells that invade other tissues. "The affinity between DNA repair factors ASCC2 and ASCC3 is reduced by cancer mutations." (PMID 34299277, 2021).
cardiovascular disease (1 paper, 2021). "Based on these evidences, we think it is reasonable to further study the role of ASCC2 in cardiovascular disease." (PMID 33686958, 2021). "However, there is no literature related to the relationship between ASCC2 and cardiovascular disease to our best knowledge." (PMID 33686958, 2021).
ASCC2 also shares sentences with these, for which no sentence is quoted: diabetes (1 paper); gastric cancer (1); heart failure (1); Obesity (1); spinal muscular atrophy (1); type 2 diabetes (1).